OPRM1 (opioid receptor mu 1)
Diseases named in the same sentence as OPRM1 in open-access papers (continued):
Sharing a sentence is not in itself a finding about the gene and the disease.
cancer (98 papers, 2012 to 2026). A tumor composed of atypical neoplastic, often pleomorphic cells that invade other tissues. "Studies examining opioid response in cancer patients have highlighted the role of genetic polymorphisms, particularly in the OPRM1 gene." (PMID 40075716, 2025). "Re-expression of OPRM1 in mouse models has been used to treat pain associated with cancer and to prevent opioid tolerance." (PMID 40910010, 2025). "The findings of our review of association studies for OPRM1 A118G in advanced cancer pain demonstrate the importance of taking ancestry into account." (PMID 38341456, 2024). "In palliative care settings for patients with advanced cancer, individuals carrying the OPRM1 AA genotype (wild type) have been associated with a more favourable phenotype, showing better response to opioids with lower dose, and fewer side effects." (PMID 38341456, 2024). "The results of our review on association studies of OPRM1 A118G in advanced cancer pain, suggest the importance of taking ancestry into account at the individual level, where possible." (PMID 38341456, 2024). "Cancer patients with an 118GG polymorphism in the OPRM1 gene need a higher morphine dose than patients with 118AA." (PMID 31547335, 2019). "To summarize, four factors were associated with the QOL in cancer patients: metastases, OPRM1 SNP, age, and gender." (PMID 28346387, 2017). "For example, genetic variants within OPRM1 have been associated with the symptom of cancer pain in four articles; and genetic variants within COMT have been associated with cancer pain in three articles." (PMID 26872611, 2016). "The observed genotype distribution of OPRM1 A118G polymorphism in both control subgroups and cancer patients conformed to the Hardy–Weinberg equilibrium (p > 0.05)." (PMID 25618602, 2015). "Over the past few years, there has been increasing interest to elucidate whether MOR or its encoding gene OPRM1 can be used as predictive biomarkers in different cancers." (PMID 34222012, 2021). "Thus, in patients with acute postoperative and cancer pain, those with the minor allele of OPRM1 require more morphine than those with the major allele." (PMID 23402298, 2013). "Similarly, OPRM1 polymorphism was associated with cognitive function in cancer patients." (PMID 39002057, 2025). "Research has shown that cancer patients with AA homozygosity of OPRM1 A118G require lower opioid doses for pain relief compared to those with G alleles." (PMID 40313598, 2025). "In a retrospective study of 250 outpatients who experience chronic non-cancer pain, there were sex differences in methylation of the promoter region the μ-opioid receptor 1 gene OPRM1 which was significantly correlated to lower rates of OUD in females." (PMID 39399686, 2024). "Genes LGALS8, PDE4DIP, RAD17, ELN, MUC4 and SEMA4D had a mid-range expression in both cancer types, while OPRM1 and ADRA1 were the least expressed, thereby corroborating the results from our box plot and survival analysis." (PMID 38544823, 2024). "Clinical, demographic, psychological, cancer treatment-related variables, quantitative sensory testing, and patient genotype (COMT, OPRM1, GCH1, ESR1, and KCNJ6) were assessed as risk factors using multiple logistic regression." (PMID 37184910, 2023). "In turn, the results of a study conducted among cancer patients with the AA OPRM1 genotype showed that they required significantly lower daily doses of morphine than patients with different genotypes due to the lower threshold of pain excitability." (PMID 36292660, 2022). "The μ-Opioid receptor gene (OPRM1) is an important element in cancer opioid analgesic effectiveness." (PMID 34253750, 2021). "The objective of this study was to determine the possible association of variations in the OPRM1, OPRK1 and COMT genes with morphine dosing for opioid therapy in Tunisians cancer patients." (PMID 29259946, 2017).
cancer (continued). "The genes OPRM1, OPRD1, and OPRK1, which encode for the classical opioid receptors (μ-, δ-, and κ-), have been implicated in the modulation of pain and potentially in the survival of cancer patients." (PMID 40075716, 2025). "The re-expression of OPRM1 in a cancer pain model may produce antinociception by mediating the effect of endogenous opioids, and OPRM1 was also one of the genes with rhythmic oscillations in neuropathic pain." (PMID 37250405, 2023). "In study regarding a large group of Scandinavian patients undergoing cancer pain treatment with opioids, no connection between OPRM1 polymorphism and pain or opioid demand was found." (PMID 38137077, 2023). "Patients with OPRM1 A/A genotype and patients with COMT Met/Met genotype have been invariably associated with a more favorable phenotype, also in specific cancer patients’ populations: less pain sensitivity, better response to opioids with lower consumption, less side effects." (PMID 32708424, 2020). "The effect of polymorphisms in the OPRM1 and COMT genes, which transcribe opioid receptor μ 1 and catechol-O-methyltransferase respectively, are relatively well categorized in their effect on acute postoperative, cancer-related and chronic pain." (PMID 31547335, 2019). "This prospective association study investigated seven variations in the OPRM1, OPRK1 and COMT gene, which encode Mu and KAPPA opioid receptors, and Catechol-O-methyltransferase enzyme respectively, in a cohort of 129 Tunisian cancer pain patients under oral morphine treatment." (PMID 29259946, 2017). "OPRM1 is the most studied pharmacogene associated with the pharmacodynamics of opioids, for a variety of pain conditions including experimentally induced pain, postoperative pain, chronic non-malignant pain and cancer pain." (PMID 38341456, 2024). "TIMER database was used for pan‐cancer analysis of different pain genes (Nav1, EHMT2, SP1, SLC6A4, COMT, OPRM1, OPRD1, CYP2D6, and CYP3A4)." (PMID 38352696, 2024). "Non-viral vector-mediated delivery of the OPRM1 gene to cancer tissues has shown efficacy in preclinical models, reducing cancer-related pain without the systemic side effects associated with traditional opioid medications." (PMID 40733067, 2025). "Conversely to our results, the literature shows that a lower OPRM1 gene expression may condition higher OUD rates in patients with long-term opioid use, such as cancer-pain patients, subjects in methadone programmes, or former heroin addicts." (PMID 37240556, 2023). "The clinical significance of pharmacogenetic biomarkers OPRM1 rs1799971, COMT rs4680 and ABCB1 (rs1045642, rs1128503, and rs2032582) should be further explored in future studies to improve precision pain management amongst Asian patients with cancer pain." (PMID 36422103, 2022). "In addition to higher DOR expression, data mining revealed that various aggressive cancer types also overexpress κ- (KOR, OPRK1) and μ- (MOR, OPRM1) opioid receptors." (PMID 33465556, 2021). "Our studies and those of others have shown that genetic factors play a key role in vulnerability to pain in cancer patients, and have identified important candidate genes such as opioid receptor genes (e.g., OPRK1 and OPRM1), catechol-O-methyltransferase (COMT), and cytokine genes." (PMID 26872611, 2016). "Associations between analgesic response and the DNA methylation level of the opioid mu receptor (OPRM1) gene (CpG sites 1–5 selected in the promoter region) were evaluated in 345 long opioid‐treated chronic non cancer pain: cases with OUD (n = 67) and controls (without OUD, n = 278)." (PMID 38949208, 2024).
tumor (55 papers, 2013 to 2025). "Soybean intake (OR = 0.425, 95%CI: 0.231–0.781) and regular sports (OR = 0.624, 95%CI: 0.399–0.976) were associated with OPRM1 hypermethylation in tumor DNA." (PMID 35024367, 2021). "A case-only study (373 cases) was designed to evaluate the effects of environmental factors on OPRM1 methylation in tumor tissue and the relationship of methylation with clinicopathological features." (PMID 35024367, 2021). "We found that OPRM1 hypermethylation in tumor tissue DNA was significantly correlated with ER status (negative vs. positive, OR = 1.945, 95%CI: 1.262–2.996) and PR status (negative vs. positive, OR = 1.611, 95%CI: 1.06–2.427)." (PMID 35024367, 2021). "In both cell lines, OPRM1 expression was significantly increased after combined treatment of D,L-methadone with all three cytotoxic drugs tested, which resulted in suppression of tumor cell growth and increase of apoptosis rates." (PMID 35182225, 2022). "Additionally, OPRM1 hypermethylation in tumor tissue DNA was significantly correlated with ER and PR negative status, and hypermethylation in PBL DNA was significantly associated with HER-2 negative status." (PMID 35024367, 2021). "Moreover, soybean intake reduced OPRM1 methylation in tumor tissue (OR = 0.425, 95%CI: 0.231–0.781)." (PMID 35024367, 2021). "We also found that soybean intake and regular sports reduced OPRM1 methylation in tumor tissue." (PMID 35024367, 2021). "Similarly, in our study, we found that OPRM1 hypermethylation was significantly associated with ER negative status and PR negative status in tumor tissue DNA (P < 0.05)." (PMID 35024367, 2021). "OPRM1 was found not to be expressed in tumor samples but only slightly in normal ones." (PMID 38544823, 2024). "MOR expression and OPRM1 gene expression in tumour tissue and non-tumour tissue was measured." (PMID 34222012, 2021). "Similarly, there were no significantly differences between normal and tumour tissue in OPRM1 expression levels (P=0.429)." (PMID 34222012, 2021).
gastrointestinal disorders (1 paper, 2025). "Additionally, polymorphisms in the OPRM1 gene may influence the manifestation of functional gastrointestinal disorders." (PMID 40910010, 2025).
OPRM1 also shares sentences with these, for which no sentence is quoted: infection (17 papers); alcoholism (15); neuropathic pain (13); Euphoria (10); non-small cell lung carcinoma (10); Pruritus (10); psychiatric disorder (9); cocaine dependence (7); injury (7); colitis (6); hepatocellular carcinoma (6); Pain (6); prostate carcinoma (6); Constipation (5); esophageal squamous cell carcinoma (4); sarcoma (4); withdrawal syndrome (4); atopic dermatitis (3); cholestasis (3); gastric cancer (3); Lewis lung carcinoma (3); lung adenocarcinoma (3); mood disorder (3); pancreatic ductal adenocarcinoma (3); adenocarcinoma (2); AIDS (2); Allergy (2); Alzheimer disease (2); autism spectrum disorder (2); Borderline personality disorder (2).
A further 99 diseases each share a sentence with OPRM1 in 2 papers or fewer.